CIMAP1B (ciliary microtubule associated protein 1B)
Synonyms: ODF3B; ODF3L3; FAP123
Tractability: No criterion of Open Targets' tractability assessment is met for any kind of drug.
Gene: Protein-coding gene on chromosome 22 (50,529,710 to 50,532,520, reverse strand). Ensembl gene ENSG00000177989.
Subcellular location: Cell projection, cilium, flagellum
Gene Ontology:
Molecular function: protein binding
Cellular component: cytoskeleton; motile cilium
Genetic constraint (gnomAD): Loss-of-function variants: 25 observed, 22.94 expected, observed/expected ratio (o/e) 1.09, 90% interval 0.79 to 1.52. The synonymous counts are far from expectation, so gnomAD's model fits this gene poorly and the ratio says little. Missense variants: 412 observed, 299.09 expected, observed/expected ratio (o/e) 1.38, 90% interval 1.27 to 1.49. Synonymous variants: 183 observed, 134.17 expected, observed/expected ratio (o/e) 1.36, 90% interval 1.21 to 1.54.
Homologues: Orthologues: chimpanzee CIMAP1B (99% identical), macaque CIMAP1B (96% identical), pig CIMAP1B (84% identical), dog CIMAP1B (76% identical), mouse Cimap1b (75% identical), guinea pig CIMAP1B (60% identical), rat Cimap1b (58% identical), tropical clawed frog cimap1a (56% identical), zebrafish trim35-30 (52% identical). Paralogues in human: CIMAP1A (46% identical), CIMAP1D (33% identical), CIMAP1C (32% identical), STPG2 (24% identical), STPG1 (16% identical).
Diseases named in the same sentence as CIMAP1B in open-access papers:
CIMAP1B is named in the same sentence as 5 diseases in open-access papers, as found by Europe PMC text mining. Sharing a sentence is not in itself a finding about the gene and the disease. The quoted sentences say what the papers report.
COVID-19 (1 paper, 2025). A disease caused by infection with severe acute respiratory syndrome coronavirus 2. "The ODF3B (ciliary microtubule associated protein 1B)–SCO2 (synthesis of cytochrome c oxidase 2) (OS) and TYMP (thymidine phosphorylase)-SCO2 (TS) chimeric isoforms made up the majority of the 14 chimeras found only in the PTBP1 knockdown and COVID-19 samples." (PMID 40110491, 2025).
CIMAP1B also shares sentences with these, for which no sentence is quoted: tumour (3 papers); Autoimmunity (1); glioma (1); multiple sclerosis (1).